ABCC5 (ATP binding cassette subfamily C member 5)
Diseases named in the same sentence as ABCC5 in open-access papers (continued):
Sharing a sentence is not in itself a finding about the gene and the disease.
acute lymphoblastic leukemia (3 papers, 2014 to 2025). Leukemia with an acute onset, characterized by the presence of lymphoblasts in the bone marrow and the peripheral blood. "In particular, the overexpression of MRP1 (ABCC1), MRP2 (ABCC2), MRP3 (ABCC3), MRP5 (ABCC5), and MRP6 (ABCC6) correlates with a poor prognosis in acute lymphoblastic leukemia in both adults and children." (PMID 36978873, 2023).
gastric cancer (3 papers, 2014 to 2021). A primary or metastatic malignant neoplasm involving the stomach. "The expression of lnc-PSCA-4:2 and lnc-ABCC5-2:1 in the plasma of gastric cancer patients was lower than healthy control, and lnc-MB21D1-3:5 was up-regulated in the plasma samples compared with healthy control." (PMID 34295803, 2021). "The expression of lnc-ABCC5-2:1, lnc-PSCA-4:2 and lnc-RNF135-1:3 in gastric cancer tissues was significantly lower than pericarcinomatous tissue." (PMID 34295803, 2021). "In the present study, we found three members of MDR related ABC transporters (ABCB1, ABCC5 and ABCG1)were targeted by miR-129-5p, which was a hyper-methylated miRNA in gastric cancer MDR cell lines." (PMID 25344911, 2014). "Once the miR-129-5p were hyper-methylated and silenced in gastric cancer cells, the expression of MDR related ABC transporters (ABCB1, ABCC5 and ABCG1) would increase and directly lead to a MDR phenotype." (PMID 25344911, 2014). "In conclusion, the present study demonstrated that miR-129-5p plays an important role in antagonizing MDR in gastric cancer cell lines by directly targeting and inhibiting three MDR-related ABC transporters--ABCB1, ABCC5 and ABCG1." (PMID 25344911, 2014).
glaucoma (3 papers, 2014 to 2024). Increased pressure in the eyeball due to obstruction of the outflow of aqueous humor. "Association analysis between ABCC5 rs1401999 and primary angle closure glaucoma in all chip-typed sample collections, de-novo genotyped sample collections, and PACG cases and clinically certified controls with open angles." (PMID 24603532, 2014). "We aimed to investigate the association between the identified susceptible genetic markers PLEKHA7 rs11024102, ABCC5 rs17217796, and KALRN rs1392912 in the progression of primary angle-closure glaucoma (PACG) in Malay patients." (PMID 34804680, 2021). "PLEKHA7 and ABCC5 gene expressions were found in structures relevant to glaucoma such as the iris, ciliary body, choroid, and aqueous humour outflow." (PMID 34804680, 2021). "PLEKHA7, ABCC5, and KALRN have been identified as susceptible genetic markers related to glaucoma." (PMID 34804680, 2021).
Insulin resistance (3 papers, 2014 to 2024). Increased resistance towards insulin, that is, diminished effectiveness of insulin in reducing blood glucose levels. "Abcc5‐/‐ mice are the opposite of the observed human overexpression phenotype, which is associated with increased visceral fat, insulin resistance, and a susceptibility to T2D with age." (PMID 31338999, 2019). "ABCC5 expression levels are in turn associated with insulin resistance, visceral fat accumulation and disease." (PMID 25117150, 2014).
pancreatic adenocarcinoma (3 papers, 2021 to 2023). "Other studies have reported that ABCC5 is expressed and functionally active in pancreatic adenocarcinoma cell lines, and it contributes to drug sensitivities." (PMID 33632224, 2021).
type 2 diabetes (3 papers, 2019 to 2025). "In humans, altered ABCC5 gene expression levels are also linked to metabolism, obesity, type 2 diabetes, and adipocyte differentiation." (PMID 41009771, 2025). "A previous genome‐wide association study linked overexpression of an ATP‐binding cassette transporter, ABCC5, in humans with a susceptibility to developing type 2 diabetes with age." (PMID 31338999, 2019). "Functionally, ABCC5 appears to impact adipocyte differentiation and GLP-1 release, implicating it in type 2 diabetes susceptibility in humans." (PMID 41009771, 2025). "Low expression of ABCC5 activated maturity onset diabetes of the young, glycosaminoglycan biosynthesis chondroitin sulfate." (PMID 37478211, 2023).
bladder cancer (2 papers, 2019 to 2023). "The roles of ABCC5, ABCA8, ABCC10, ABCB10, ABCG1, ATP7B, ABCG2, and mitochondrial SLC25A10 in platinum-receiving urinary bladder cancer patients should be the subject of further investigation." (PMID 36650399, 2023).
cervical cancer (2 papers, 2022 to 2025). A primary or metastatic malignant neoplasm involving the cervix. "The association between FOXM1, ATP-binding cassette subfamily C member 5 (ABCC5), and cervical cancer cell drug resistance was assessed by overexpressing or knocking down the expression of FOXM1 in Caski or Caski/Taxol cells." (PMID 35141332, 2022). "FOXM1 promotes drug resistance in cervical cancer cells by regulating ABCC5 gene transcription." (PMID 35141332, 2022). "In conclusion, FOXM1 may promote drug resistance in cervical cancer cells by regulating ABCC5 gene transcription." (PMID 35141332, 2022). "The present study assessed whether resistance to paclitaxel was increased following upregulation of FOXM1 and ABCC5 in cervical cancer cells." (PMID 35141332, 2022).
depression (2 papers, 2021 to 2025). "Furthermore, ABCC5 has been linked via GWAS to cognitive ability, including memory and depression in humans, mice, and rats, and the ABCC5 protein is known to be expressed in human pyramidal neurons." (PMID 41009771, 2025).
diabetes (2 papers, 2019 to 2021). "This is in line with recent in vivo evidence that a novel T2D cis-gene previously mapped using the same method, ABCC5, was functionally implicated in diabetes by improving insulin sensitivity and reducing fat mass when knocked-out in mice." (PMID 34456865, 2021). "The role of ABCC5 in diabetes and obesity remains unexplored, and any link between ABCC5 overexpression and increased fat stores is unknown." (PMID 31338999, 2019). "Currently, the role of ABCC5 in diabetes and obesity is unknown." (PMID 31338999, 2019).
dyslipidemia (2 papers, 2010 to 2019). "For example, some genes (e.g. ABCC5) are known to be related to energy metabolism, but are they truly involved in obesity-metabolic syndrome?" (PMID 21062472, 2010). "Cholesterol and triglyceride plasma profiles showed decreased levels of total cholesterol, LDL, glycerol, and triglycerides in both female and male Abcc5‐/‐ mice, which would suggest that Abcc5‐/‐ mice did not have dyslipidemia." (PMID 31338999, 2019).
osteosarcoma (2 papers, 2021 to 2022). A usually aggressive malignant bone-forming mesenchymal neoplasm, predominantly affecting adolescents and young adults. "Genetic variants in ABCC3, ABCC5, FasL, GLDC and GSTP1 were repeatedly associated to osteosarcoma treatment outcome, using very heterogeneous efficacy outcomes." (PMID 36536332, 2022).
Pseudoxanthoma elasticum (2 papers, 2007 to 2024). "ABCC5 can therefore be added to the list of abundant ABC transporters with a function in the eye which for example includes ABCA4, the gene underlying Stargardt's disease and ABCC6, the gene implicated in pseudoxanthoma elasticum." (PMID 17521428, 2007).
Barrett's oesophagus (1 paper, 2016). "The risk locus near HTR3C and ABCC5 alone accounts for only a fraction of the phenotypic variance; the OR is 1·17 between patients with oesophageal adenocarcinoma and controls, and 1·02 between individuals with Barrett's oesophagus and controls." (PMID 27527254, 2016). "To our knowledge, we have identified for the first time an oesophageal adenocarcinoma association near the HTR3C and ABCC5 genes that is not observed in Barrett's oesophagus." (PMID 27527254, 2016). "The locus identified near HTR3C and ABCC5 (rs9823696) was associated specifically with oesophageal adenocarcinoma (p=1·6 × 10−8) and was independent of Barrett's oesophagus development (p=0·45)." (PMID 27527254, 2016). "Furthermore, the specific association between oesophageal adenocarcinoma and the locus near HTR3C and ABCC5 might constitute a novel genetic marker for prediction of the transition from Barrett's oesophagus to oesophageal adenocarcinoma." (PMID 27527254, 2016).
cardiac hypertrophy (1 paper, 2015). "Three of them (ABCC4, ABCC5, and ABCC11) are expressed in cardiac tissue but ABCC4 is the most studied and has been shown to enhance cAMP formation, contractility, and cardiac hypertrophy." (PMID 26483685, 2015). "Three of them (MRP4 aka ABCC4, MRP5 aka ABCC5, and MRP8 aka ABCC11) have the ability to actively extrude cAMP and cGMP from the cell and in cardiac myocytes, MRP4 has been shown to enhance cAMP formation, contractility, and cardiac hypertrophy." (PMID 26483685, 2015).
ischemic cardiomyopathy (1 paper, 2023). Ischemic cardiomyopathy is a cardiomyopathy in which a weakness in the muscle of the heart due to inadequate oxygen delivery to the myocardium with coronary artery disease being the most common cause. "ABCC5 is found in cardiomyocytes as well as endothelial cells, and its expression is enhanced in ischemic cardiomyopathy, which is defined as systolic left ventricular failure in the presence of obstructive coronary artery disease." (PMID 38139840, 2023).
leukaemia (1 paper, 2024). "Even though in most tumorigenesis and doxorubicin drug resistance, P-gp is the pioneer reprehensive of ABC transporters targeted by miRNAs, in leukaemia, some other little-known members comprising of ABCE1, ABCC5, and ABCC10 have been inferred in this process." (PMID 39679367, 2024). "miRNAs have the utmost importance in overcoming chemoresistance in leukaemia by targeting ABC transporters like P-gp and others, such as ABCE1, ABCC5, and ABCC10." (PMID 39679367, 2024). "The most contemplative case in ABC transporter-related chemoresistance may affiliated with ABCC5 and ABCC10, where they exhibited antiapoptotic and proliferative properties except for the drug efflux ability in leukemia doxorubicin resistance cells." (PMID 39679367, 2024). "Notably, similar to the role of ABCC5 and ABCC10 in modulating proliferation and apoptosis in leukaemia, ABCE1 knockdown significantly suppressed H69/ADR cell growth, augmented the cell cycle inhibition rate, and promoted apoptosis." (PMID 39679367, 2024).
liver diseases (1 paper, 2025). "Studies have highlighted the elevated expression of ABCC5 in liver diseases and its substantial impact on HCC progression, garnering significant attention." (PMID 40860808, 2025).
oesophageal adenocarcinoma (1 paper, 2016). "We also identified a risk variant near HTR3C/ABCC5 that was associated solely with development of oesophageal adenocarcinoma." (PMID 27527254, 2016). "However, on the functional level, ABCC5 represents an interesting oesophageal adenocarcinoma candidate gene." (PMID 27527254, 2016).
oral-cancer (1 paper, 2015). "Differentially expressed microRNAs have been found to tightly regulate four of the possible biomarkers that we identified—HMGA2, EGFR, HOXA1, and ABCC5/ABCC4 —further supporting their involvement in oral-cancer progression." (PMID 26179909, 2015).
prostate neoplasm (1 paper, 2025). A neoplasm (disease) that involves the prostate gland. "Although the provided references do not directly address the association of prostate neoplasm with the ABCC5, HYAL2, and SLC9A1 proteins, it appears that the HMMR-rs299295 and STAB2-rs2271637 variants may play a role in the growth, proliferation, and metastasis of prostate neoplasm." (PMID 40567905, 2025).
psoriasis (1 paper, 2022). An autoimmune condition characterized by red, well-delineated plaques with silvery scales that are usually on the extensor surfaces and scalp. "Typically, CISD1 (p = 3.9e-10), TRIB2 (p < 2.22e−16), and ABCC5 (p=0.0012) levels among psoriasis cases increased compared with healthy controls, whereas PRKAA2 (p < 2.22e−16), ACSF2 (p = 3e−15), TIMM9 (p= 0.049), PEBP1 (p < 2.22e−16) and NR5A2 (p=1.8e−13) levels decreased among psoriasis cases." (PMID 36685512, 2022). "Typically, ABCC5 (p = 0.0012), CISD1 (p= 3.9e−10) and TRIB2 (p < 2.22e−16) levels in psoriasis cases increased compared with healthy samples, whereas NR5A2 (p = 1.8e−13), PEBP1 (p < 2.22e−16) and PRKAA2 (p < 2.22e−16) levels decreased in psoriasis samples." (PMID 36685512, 2022).
retinal disease (1 paper, 2007). "This may also shed light onto a possible contribution of ABCC5 to retinal disease." (PMID 17521428, 2007). "So far, a role for ABCC5 in retinal disease has not been determined." (PMID 17521428, 2007).
schizophrenia (1 paper, 2025). A major psychotic disorder characterized by abnormalities in the perception or expression of reality. "Interestingly, in line with the presentation of schizophrenia in humans, male Abcc5−/− mice showed a much more pronounced cognitive phenotype compared with female littermates, and female Abcc5−/− mice were able to compensate for the loss of Abcc5 activity to some degree." (PMID 41009771, 2025).
Stroke (1 paper, 2012). Sudden impairment of blood flow to a part of the brain due to occlusion or rupture of an artery to the brain. "ABCC5 and ABCG2 showed elevated expression after ischemia in a rat model for stroke." (PMID 22553972, 2012).
T-cell lymphomas (1 paper, 2015). "It was found that there were significant differences in ABC-transporter expression between B- and T-cell lymphomas, with T-cell lymphomas showing a higher ABCB5 and ABCC5, and lower ABCC1 expression compared to B-cell lymphomas." (PMID 29061939, 2015).
cancer (45 papers, 2010 to 2025). A tumor composed of atypical neoplastic, often pleomorphic cells that invade other tissues. "Studies show that ABCC5 is closely associated with key cancer traits like drug resistance, metastasis, and proliferation." (PMID 40860808, 2025). "ATP binding cassette subfamily C member 5 (ABCC5), also called multidrug resistance-associated protein 5, has been reported to play an essential cancer-promoting role in various tumors 16-19." (PMID 33994848, 2021). "The literature on rodent Abcc5 and human ABCC5 dovetails into studies which investigates the loss of function of Abcc5 in knock-out mouse models or the regulation at gene expression level in human cancers." (PMID 40593462, 2025). "And ABCC5 is associated with the survival and prognosis of some cancers." (PMID 39563862, 2024). "ABCC5 is associated with the survival and prognosis of some cancers." (PMID 39563862, 2024). "In addition, high ABCC5 expression is closely associated with drug resistance in cancer therapy." (PMID 39563862, 2024). "Human ABCC5 gene expression is well established to be upregulated in several cancers, including breast, lung, liver, colorectal, pancreatic, ovarian, prostate, cervical, and nasopharyngeal tumours." (PMID 41009771, 2025). "This approach offers new perspectives on the re-utilization of ZDV and other nucleoside analogs in HCC treatment, emphasizing the importance of targeting the transporter protein ABCC5 to improve drug delivery and overcome cancer drug resistance." (PMID 40860808, 2025). "In this study, the ABCC5 scoring module genes were significantly enriched in cell cycle signaling pathways, which involve various regulatory proteins that play key roles in cancer progression." (PMID 40860808, 2025). "Given its regulation by multiple pathways across cancers, ABCC5 is a promising therapeutic target, particularly for overcoming drug resistance and metastasis." (PMID 40860808, 2025). "Aberrant expression of ATP-binding cassette subfamily C member 5 (ABCC5), a member of the ABC transporter family, is linked to various cancers and plays a crucial role in regulating cancer cell function." (PMID 40860808, 2025). "By modulating critical molecules in the tumor microenvironment (TME), ABCC5 helps cancer cells evade therapy and potentially enhances invasion and metastasis." (PMID 40860808, 2025). "Previous studies have largely overlooked the co-expression networks influenced by ABCC5, focusing primarily on its direct impact on cancer cells." (PMID 40860808, 2025). "ABCC5, a key transporter protein, plays a crucial role in pyrimidine metabolism and protein homeostasis—processes essential for cancer cell survival and proliferation." (PMID 40860808, 2025). "ABCC5 is regulated by corresponding regulatory pathways in a variety of cancers; thus, we organized information regarding relevant regulatory pathways." (PMID 39563862, 2024). "Second, side effects: since ABCC5 is not only expressed in cancer cells but also functions in normal tissues, one of the main challenges in developing specific inhibitors is how to minimize the effects on normal cells." (PMID 39563862, 2024). "Preclinical models: Most of the current studies are limited to in vitro cellular experiments and animal models, and a wider range of preclinical models are needed to validate the effect of inhibiting ABCC5 on different cancer types." (PMID 39563862, 2024). "This review examined the expression, structure, function, and role of ABCC5 in various cancer types." (PMID 39563862, 2024). "A key role of ABCC5 is to facilitate drug efflux and reduce effective concentrations of drugs in cancer cells." (PMID 39563862, 2024). "Many recent investigations have provided evidence of the role of ABCC5 in drug resistance in different forms of cancer." (PMID 39563862, 2024). "Fewer studies have been conducted on ABCC5, and there is minimal literature detailing the role of ABCC5 in cancer drug resistance." (PMID 39563862, 2024).